GMNN (geminin DNA replication inhibitor)
Description:
Inhibits DNA replication by preventing the incorporation of MCM complex into pre-replication complex (pre-RC). It is degraded during the mitotic phase of the cell cycle. Its destruction at the metaphase-anaphase transition permits replication in the succeeding cell cycle. Inhibits histone acetyltransferase activity of KAT7/HBO1 in a CDT1-dependent manner, inhibiting histone H4 acetylation and DNA replication licensing. Inhibits the transcriptional activity of a subset of Hox proteins, enrolling them in cell proliferative control.
Synonyms: Gem; MGORS6
Tractability: Small molecule: it belongs to a druggable protein family. PROTAC: ubiquitination databases record sites on it; a small molecule that binds it is known.
Gene: Protein-coding gene on chromosome 6 (24,774,892 to 24,786,103, forward strand). Ensembl gene ENSG00000112312.
Subcellular location: Cytoplasm; Nucleus
Subcellular location (Human Protein Atlas): Nucleoplasm; Basal body; Cytosol
Pathways (Reactome):
DNA Replication: Activation of the pre-replicative complex; Assembly of the pre-replicative complex; Switching of origins to a post-replicative state
Gene Ontology:
Molecular function: chromatin binding; histone deacetylase binding; protein binding; transcription coregulator activity; DNA-binding transcription factor binding; transcription corepressor activity
Biological process: negative regulation of cell cycle; negative regulation of DNA replication; negative regulation of DNA-templated DNA replication; negative regulation of DNA-templated transcription; negative regulation of mitotic DNA replication initiation; regulation of DNA replication; regulation of DNA-templated DNA replication initiation; regulation of mitotic cell cycle; protein-containing complex assembly
Cellular component: cytoplasm; nucleoplasm; nucleus; transcription repressor complex
Gene-disease validity (ClinGen):
ClinGen rates the evidence that GMNN causes each of these diseases.
Meier-Gorlin syndrome 6 (autosomal dominant): Moderate.
Homologues: Orthologues: chimpanzee GMNN (99% identical), macaque GMNN (94% identical), guinea pig GMNN (80% identical), pig GMNN (80% identical), rabbit GMNN (79% identical), mouse Gmnn (78% identical), dog GMNN (76% identical), rat Gmnn (60% identical), tropical clawed frog gmnn (47% identical), zebrafish gmnn (41% identical), Drosophila melanogaster geminin (23% identical). Paralogues in human: MCIDAS (23% identical), GMNC (18% identical).
Diseases named in the same sentence as GMNN in open-access papers:
GMNN is named in the same sentence as 22 diseases in open-access papers, as found by Europe PMC text mining. Sharing a sentence is not in itself a finding about the gene and the disease. The quoted sentences say what the papers report.
breast carcinoma (5 papers, 2013 to 2025). "GMNN overexpression has been observed in breast cancer, and it is associated with a poor prognosis." (PMID 38600056, 2024). "GMNN, another cell cycle regulator, is overexpressed in liver, colorectal, pancreatic, and breast cancers." (PMID 39859485, 2025). "SiRNAs targeting GMNN (siGEM) were shown to induce DNA re-replication in colorectal carcinoma, head and neck squamous cell carcinomas (HNSCCs), and breast cancer." (PMID 34658851, 2021).
liver cancer (4 papers, 2012 to 2025). An epithelial or non-epithelial malignant neoplasm that arises from the liver. "We found that 5.0 fold and 3.4 fold increases of CENPF and GMNN gene expression were observed in liver cancer tissues, respectively." (PMID 22912832, 2012).
melanoma (3 papers, 2009 to 2022). A malignant, usually aggressive tumor composed of atypical, neoplastic melanocytes. "Previous studies have demonstrated that GMNN expression was correlated with prognosis in oral squamous cell carcinoma, squamous cell carcinoma of the tongue, and melanoma." (PMID 36539849, 2022). "The GMNN gene was amplified in 31.4% of cancer cell lines, with very high amplification rates in melanoma (71%; n = 5/7) and gastric cancer cell lines (80%; n = 4/5)." (PMID 22912832, 2012). "MCM4 combined with GMNN overexpression as found in our material, is also predictive for metastasis and poor survival in melanoma, documented in a large prospective microarray study." (PMID 19662092, 2009).
gastric cancer (2 papers, 2011 to 2012). A primary or metastatic malignant neoplasm involving the stomach. "Prominent validated targets include CDK6, MYC, CCNE2, MET and GMNN and we furthermore validated the regulation of HDAC1 and SIRT1 also in gastric cancer cells." (PMID 21418558, 2011).
Meier-Gorlin syndrome (2 papers, 2017 to 2022). "Meier-Gorlin syndrome (MGS) is caused by mutations in components of the prereplication and pre-initiation DNA replication complexes (ORC1, ORC4, ORC6, CDT1, CDC6, GMNN, CDC45), which license replication origins and mediate loading and functioning of the replication fork helicase." (PMID 28630177, 2017).
asthenozoospermia (1 paper, 2025).
colon cancer (1 paper, 2012). "Of these, the following four genes were common to both HCC and colon cancer: CENPF, GMNN, CDK13, and FAM82B." (PMID 22912832, 2012).
Fanconi anemia (1 paper, 2022). Fanconi anemia (FA) is a hereditary DNA repair disorder characterized by progressive pancytopenia with bone marrow failure, variable congenital malformations and predisposition to develop hematological or solid tumors. "KEGG pathway analysis manifested that GMNN upregulated genes implicated in cell cycle, spliceosome, DNA replication, proteasome, pyrimidine metabolism, ribosome, Fanconi anemia pathway, oxidative phosphorylation, mismatch repair, nucleotide excision repair, base excision repair, and oocyte meiosis." (PMID 36601056, 2022).
cancer (13 papers, 2011 to 2025). A tumor composed of atypical neoplastic, often pleomorphic cells that invade other tissues. "In TCGA, whole-genome sequencing results, 57 mutations in the GMNN gene were identified in 13 cancer types." (PMID 34658851, 2021). "Yet, the mapped genes were highly relevant to PCa etiology and included known cancer drivers LDLRAD4, GMNN, COL1A1, CD38, PTPRN2, GTSE1 and CAMK2N1 in the risk signature and KLK2, AR, KLK3, SPDEF in the relapse signature." (PMID 33845808, 2021). "We also found that three genes – CENPF, GMNN and CDK13 – were frequently amplified in various human cancers and were significantly associated with several pathophysiological phenotypes in HCC." (PMID 22912832, 2012). "Induction of DNA re-replication in cancer cells increases nuclear size and siRNAs against 11 of these genes increased the cell's nuclear area at least 70% as much as the 1.6-fold increase induced by siRNAs against either GMNN." (PMID 27144335, 2016). "Certain studies have shown that miR-449 could directly target and switch off the expression of GMNN, MET, CCNE2 and another cancer-related genes, the majority of which are associated with the cell cycle, by syncretizing with the 3′UTR of target genes." (PMID 25202363, 2014). "The identification of the amplified genes CENPF, GMNN, and CDK13 in tumors provides new insight into the carcinogenesis process, and suggests that these genes can be used as novel cancer markers for the development of diagnostic, prognostic, and/or targeted therapies." (PMID 22912832, 2012). "In addition, GMNN has been reported to be an inhibitor of cell proliferation and a potential tumor suppressor gene that is expressed at high levels in various cancer cell lines and in primary tumors." (PMID 22912832, 2012). "Furthermore, inhibiting GMNN activity could selectively arrest cancer cell proliferation by inducing DNA damage-mediated apoptosis and DNA re-replication without affecting the normal cells." (PMID 36539849, 2022). "Thus, mutations in the GMNN gene are not widespread in human cancers." (PMID 34658851, 2021). "Taken together, our results suggest that coincidently amplified CDK13, GMNN, and CENPF genes can play a role as common cancer-driver genes in human cancers." (PMID 22912832, 2012). "Collectively, these results suggest that CENPF, GMNN, and CDK13 play a role in the tumorigenesis of human cancers." (PMID 22912832, 2012). "Our results suggest that inhibition of the amplified genes, CENPF, GMNN and CDK13, might be an effective new therapeutic strategy against human cancer." (PMID 22912832, 2012).
tumor (7 papers, 2012 to 2024). "The overexpression of GMNN accelerates tumor progression, while the depletion of GMNN inhibits tumor growth and metastasis, underscoring its significance in ACC pathogenesis." (PMID 39682247, 2024). "The GMNN-mediated dysregulation of DNA replication licensing may contribute to genomic instability and the accumulation of genetic alterations, driving tumor evolution and metastasis." (PMID 39682247, 2024). "Interestingly, the oncogenic activity of these genes (excluding FAM82B) was highly correlated with gene-copy numbers in tumor samples (correlation coefficient, r>0.423), indicating that amplifications of CENPF, GMNN, and CDK13 genes are tightly linked and coincident in tumors." (PMID 22912832, 2012). "In conclusion, we constructed a five DEGs (CCNB2, CDK1, DTL, GMNN, and UBE2C)-based prognostic signature for ACC and first identified GMNN as a novel tumor biomarker for predicting the malignant progression, mitotane efficacy, and prognosis of ACC." (PMID 36539849, 2022). "Eight miRNA-449-family target genes (CDC25A, SIRT1, GMNN, E2F1, E2F3, BCL2, CDK2, and CCNE2) were selected; all of them involved in tumor development, cell cycle, and apoptosis." (PMID 30926829, 2019). "Furthermore, the high correlation between copy numbers of CENPF, GMNN, and CDK13 suggests that these three amplified genes utilize and/or share the same tumor-development pathway." (PMID 22912832, 2012). "In addition, because no somatic point mutations in CDK13, GMNN, or CENPF genes were detected in primary tumor tissues, we think that the oncogenic effects of these genes are mainly due to alterations in gene copy numbers, particularly gene amplification." (PMID 22912832, 2012).
infection (2 papers, 2019 to 2020). The state of being infected such as from the introduction of a foreign agent such as serum, vaccine, antigenic substance or organism. "In contrast, GMNN mRNA levels were either similar to uninfected or increased in the late stages of infection by 2-fold." (PMID 32295923, 2020). "Since the progression of infection depends on the cell cycle, we also probed mRNA levels for the cell cycle markers GMNN and TOP2A introduced in the previous sections." (PMID 31653857, 2019).
GMNN also shares sentences with these, for which no sentence is quoted: colorectal cancer (2 papers); breast tumors (1); cervical cancer (1); cervix adenocarcinoma (1); head and neck squamous cell carcinoma (1); hepatocellular carcinoma (1); oral squamous cell carcinoma (1); osteosarcoma (1); pancreatic cancer (1); skin melanoma (1); squamous cell carcinoma of the tongue (1).